RNU6-13P (RNA, U6 small nuclear 13, pseudogene)
Synonyms: RNU6-13
Gene: Small nuclear RNA gene on chromosome 8 (56,917,084 to 56,917,190, forward strand). Ensembl gene ENSG00000206975.
Homologues: Orthologues: mouse Gm24641 (100% identical), pig U6 (100% identical), rat U6 (100% identical). Paralogues in human: RNU6-12P (100% identical), RNU6-32P (100% identical), RNU6-1 (99% identical), RNU6-17P (99% identical), RNU6-18P (99% identical), RNU6-2 (99% identical), RNU6-3P (99% identical), RNU6-4P (99% identical), RNU6-5P (99% identical), RNU6-6P (99% identical), RNU6-9 (99% identical), RNU6-25P (98% identical), and 1290 more.